HSPB1 (heat shock protein family B (small) member 1)
Diseases named in the same sentence as HSPB1 in open-access papers (continued):
Sharing a sentence is not in itself a finding about the gene and the disease.
atherosclerosis (12 papers, 2012 to 2025). A disease characterized by the build-up of fatty material and calcium deposition in the arterial wall resulting in partial or complete occlusion of the arterial lumen. "HSPB1 downregulation is even greater in complicated lesions, raising the possibility that HSPB1 deficiency plays a role in atherosclerosis progression." (PMID 29240668, 2017). "It plays an antiatherogenic role, modulates inflammation and oxidative stress in vascular as well as in cardiac myocytes, stimulates autophagocytosis, suppresses apoptosis; low circulating level of HSPB1 is seen as an emerging marker of atherosclerosis." (PMID 40514620, 2025). "Therefore, the decrease of HSPB1 in serum of patients with coronary artery disease may be caused by over‐activation of protease, or excessive consumption of HSPB1 caused by anti‐ferroptosis in the body in the process of atherosclerosis plaque formation, which needs further study." (PMID 35152560, 2022). "Plasma phosphorylated HSPB1 has been reported to be involved in the pathogenesis of several diseases such as atherosclerosis and chronic kidney disease." (PMID 34239687, 2021). "HSPB1 is also released in the extracellular space and recent studies suggest that eHSPB1 plays an important role in atherosclerosis." (PMID 29240668, 2017). "There is evidence of a beneficial effect of HSPB1 overexpression in animal models of atherosclerosis and in diabetic animals with DSP." (PMID 29240668, 2017). "The key experiment was the crossing of transgenic mice overexpressing HspB1 with apoE−/− mice that develop atherosclerosis when fed a high-fat diet." (PMID 24278676, 2012). "It is also well-known that, in men and women, HspB1 shows an attenuated expression in human coronary arteries as the extent of atherosclerosis progresses." (PMID 24278676, 2012). "It is well documented that a low level of HSPB1 may be a potential biological indicator of atherosclerosis." (PMID 36474716, 2022). "HSPB1 may be an important molecule for reducing the occurrence and development of atherosclerosis, and it is also an important molecular target for the treatment of ASO." (PMID 36474716, 2022). "Hspb1 could inhibit reactive oxygen species (ROS) and has a protection effect against atherosclerosis and coronary heart disease." (PMID 34220548, 2021). "Recent reports demonstrated that secreted-type HSPB1 could be a potential index of atherosclerosis and biomarker of diabetic nephropathy." (PMID 34239687, 2021). "Heat shock proteins were also found to be present as extracellular proteins, and concentrations of these have been found to vary in many conditions, including HSPB1 and HSPA1A in cancer, cardiovascular disease, HSPB1 in atherosclerosis and HSPA1A in rheumatoid arthritis." (PMID 37583307, 2023).
diabetes (10 papers, 2010 to 2025). "Diabetes significantly decreased HSPB1 and MGST1 levels and increased ferroptosis compared to normal group." (PMID 39711549, 2024). "The levels of HspB1 are decreased in the rat diabetic retina, despite an elevation of its mRNA levels, suggesting either enhanced degradation or chemical modification." (PMID 35480891, 2022). "In turn HSPB1 has been related to better fatigue resistance and has been shown to be up-regulated in animal models of diabetes-related muscle weakness." (PMID 28468631, 2017). "In summary, levels of HSPB1/phosphorylated HSPB1 are either unchanged or enhanced in diabetes microvascular complications." (PMID 29240668, 2017). "However, one study in mice (after 10 weeks of streptozotocin-induced diabetes) reported a significant increase in HspB1 mRNA and protein levels in the retina." (PMID 35480891, 2022). "However, proinflammatory cytokines that are generally upregulated in the diabetic retina reduce the levels of HspB1 in retinal capillary endothelial cells, which could lead to their apoptosis in diabetic retinopathy." (PMID 35480891, 2022). "Similarly, in the retina, diabetes does not evoke the expected HSP response as total HSPB1 was unchanged, HSPD1/HSP60 was reduced in the mitochondria, HSPC/HSP90 was downregulated and only HSPA/HSP70 underwent upregulation." (PMID 29240668, 2017). "Deletion of MK2, which phosphorylates HSPB1, was not beneficial in an animal model of streptozotocin (STZ)-induced diabetes, failing to show a functional relevance of the p38/MK2/HSPB1 pathway in DN." (PMID 29240668, 2017).
lung carcinoma (10 papers, 2015 to 2024). "Studies have reported that increased expression of HSPB1 is highly associated with poor prognosis in lung cancer through enhanced cell migration and invasion." (PMID 37241117, 2023). "The SNPs of HSPB1 rs7459185 was associated with radiation esophagitis in lung cancer through the regulation of HSPB1 expression level." (PMID 32848724, 2020). "Lung cancer patients who carry the HSPB1 rs2070804 T allele or HSPA4 rs3088225 A allele may have a better prognosis compared to the rs2070804 G allele or HSPA4 rs3088225 G allele." (PMID 32848724, 2020). "We found that the genetic polymorphism of HSPB1 rs2070804 (G>T) was significantly associated with the overall survival (OS) of lung cancer patients in additive and dominant models [Additive model: p=0.041, OR=0.66, 95%CI, (0.45–0.98); Dominant model: p=0.015, OR=0.55, 95%CI, (0.34–0.89)]." (PMID 32848724, 2020). "The functional HSPB1 promoter -1271G>C variant may affect lung cancer susceptibility and survival time by modulating endogenous HSPB synthesis levels." (PMID 32848724, 2020). "The present study is conducted to investigate whether the genetic polymorphisms of LIG4 and HSPB1 are involved in the increased risk of RILI among patients with lung cancer after radiotherapy." (PMID 25811031, 2015). "Previous studies showed that HSPB1 was highly expressed in a variety of human cancers, including lung cancer." (PMID 35526007, 2022). "In conclusion, those patients carrying the HSPB1 T allele rs2070804 and the allele A of HSPA4 rs3088225m are carriers of the protective allele in terms of the prognosis of lung cancer." (PMID 32848724, 2020). "In conclusion, we found that the polymorphisms of HSPB1 rs2070804 and HSPA4 rs3088225 were significantly associated with the prognosis in lung cancer patients treated with platinum-based chemotherapy." (PMID 32848724, 2020). "We found that the polymorphisms of HSPB1 rs2070804 and HSPA4 rs3088225 were significantly associated with lung cancer survival (p=0.015, p=0.049*, respectively)." (PMID 32848724, 2020). "Except for the polymorphisms of HSPB1 rs2070804 and HSPA4 rs3088225, we also found other polymorphisms which are associated with lung cancer prognosis in some specific subgroups." (PMID 32848724, 2020). "In conclusion, the HSPB1 rs2070804 T allele and HSPA4 rs3088225 A allele are the protective allele in the prognosis of lung cancer patients treated with platinum-based chemotherapy." (PMID 32848724, 2020). "Association of the HSPB1 rs2070804 polymorphisms and OS, HSPA4 rs3088225 polymorphisms and PFS in lung cancer patients." (PMID 32848724, 2020). "In this study, we found that the HSPB1 rs2070804 and HSPA4 rs3088225 polymorphisms are significantly associated with the prognosis in lung cancer patients with the platinum-based chemotherapy treatment." (PMID 32848724, 2020). "In the present study, the primary objectives were to investigate the incidence of RP of lung cancer patients after the treatment of radiotherapy and to analyze the association between the LIG4 and HSPB1 genes polymorphisms and RILI in lung cancer patients." (PMID 25811031, 2015). "Furthermore, samples from various types of human lung cancer, including small-cell, large-cell, and squamous cell carcinoma and adenocarcinoma, showed high levels of HSPB1 expression in TECs." (PMID 35130955, 2022). "In particular, the high expression of HSPB1 has been associated with poor prognosis in several carcinomas and osteosarcomas, while CH60, with annexin-2, is considered a potential biomarker for subtypes of lung carcinoma." (PMID 28686225, 2017). "We suspected that the different pathological types in lung cancer may result in the differences in genotype distribution frequency of HSPB1, and the frequency of genotype at the same site (rs2868371) may differ in different ethnicity." (PMID 25811031, 2015).
lung carcinoma (continued). "The genotypes of HSPB1 rs2070804 and HSPA4 rs3088225 may be an attractive biomarker used to predict the prognosis of platinum-based chemotherapy lung cancer patients." (PMID 32848724, 2020). "The results of our study suggest that HSPB1 rs2070804 (G>T) and HSPA4 rs3088225 (A>G) may be useful biomarkers for predicting the prognosis of lung cancer patients treated with platinum-based chemotherapy." (PMID 32848724, 2020). "In the lung cancer group, PRKG2 exhibited significant positive correlation with NFE2L2, SLC40A1, TFRC, and significant negative correlation with CHAC1 and HSPB1." (PMID 39744538, 2024). "In non-tumorigenic BEAS-2B cells and A549 lung cancer cells, the elevated levels of HSF2 promote cell proliferation and migration, which is partially dependent on HSF2’s ability to induce the expression of HSP27/HSPB1 and HSP90/HSPC." (PMID 32408596, 2020).
myocardial infarction (10 papers, 2012 to 2024). Gross necrosis of the myocardium, as a result of interruption of the blood supply to the area, as in coronary thrombosis. "Myocardial infarction causes an increase in reticulon 3, which binds to and recruits heat shock protein beta‐1 (HSPB1) into the endoplasmic reticulum, resulting in a decrease in the content of HSPB1 in the cytoplasm." (PMID 38420163, 2024). "HSPB1 expression in cardiomyocytes is upregulated after myocardial infarction, and cardiomyocyte-specific HSPB1 deficiency promotes adverse remodeling after myocardial infarction, leading to cardiac dysfunction, cardiac rupture, and increased mortality." (PMID 39711549, 2024). "Interestingly, the redox oscillation of HSPB1 exhibits a circadian rhythm, which is associated with higher rates of acute myocardial infarction in the morning." (PMID 37566026, 2023). "HSPB1 is a negative regulator of the cardiomyocyte inflammatory response and is essential for repairing injured heart tissue following myocardial infarction." (PMID 37287974, 2023). "HSPB1 was up-regulated in mice cardiomyocytes as a response to myocardial infarction and involved in repairing tissue damaged by inhibiting NFκB inflammatory signaling." (PMID 34211507, 2021). "HspB1 and HspB5 stimulate, through their holdase activity, the cellular resistance by attenuating aggregates formation, as for example, in myocardial infarction and cerebral ischemia." (PMID 24278676, 2012). "The in vivo protective activity of these proteins as potent suppressors of cell degeneration was further confirmed in transgenic mice overexpressing HspB1 that are strongly protected against myocardial infarction and cerebral ischemia." (PMID 24278676, 2012). "Cardiomyocyte HSPB1 is required for wound healing after myocardial infarction (MI) and could be a target for myocardial repair in MI patients." (PMID 34239687, 2021). "This HSP27 (HSPB1) phenotype in platelets could thus represent a measurable stress response in myocardial infarction and potentially other acute ischemic events." (PMID 31783528, 2019). "Additionally, expression of HSPB1 in cardiomyocytes is necessary for wound healing after myocardial infarction, suggesting that this protein may be a target for enhancement of repair after myocardial infarction." (PMID 36204316, 2022). "HSPB1 knockout mice subjected to myocardial infarction (MI) exhibited enhanced and prolonged leukocyte infiltration, enhanced inflammatory cytokine expression, and enhanced toll-like receptor 4 (TLR4)/myeloid differentiation factor 88 (MyD88)/NF-κB activation in their heart tissue." (PMID 37252119, 2023).
Alzheimer disease (9 papers, 2020 to 2025). A progressive, neurodegenerative disease characterized by loss of function and death of nerve cells in several areas of the brain leading to loss of cognitive function such as memory and language. "HSPB1 protective role has been better investigated in other NDs: for instance, HSPB1 enhanced expression by indole compounds associated with beneficial effects on mouse models of Alzheimer disease and polyQ-associated spinocerebellar ataxia." (PMID 36233058, 2022). "In fact, the machine learning approach places HspB1 along with amyloid precursor protein (APP) as a biomarker for Alzheimer’s disease." (PMID 40003991, 2025). "Immunoprecipitation experiments have shown that extracellular HSPB1 can interact with extracellular Aβ, the primary component of amyloid plaques found in the brains of Alzheimer’s disease patients." (PMID 40385290, 2025). "In Alzheimer’s disease (AD) models, HSPB1 bound to Aβ1-40 and decreased aggregation and cytotoxicity in cerebrovascular organotypic cultures." (PMID 40385290, 2025). "HSPB1 is significantly up-regulated in the cortex of Alzheimer disease and is also significantly increased in the cortex of Parkinson’s patients." (PMID 34488523, 2021). "Crossing the APPswe/PS1dE9 mouse model for Alzheimer’s disease with a mouse model that overexpresses HSPB1 led to significant improvements in spatial learning and electrophysiological parameters." (PMID 32323160, 2020). "HspB1 differential regulation also correlates with Alzheimer’s disease (AD)." (PMID 40003991, 2025). "In the present study, we proposed that up-expressed HSPB1 positive regulated PIP5K1C-46721-AT might be linked to the tumorigenesis, metastasis and poor prognosis of PRAD through pathways related to Alzheimer's disease." (PMID 37010714, 2023). "Despite these limitations, we proposed that aberrant HSPB1 regulated PIP5K1C-46721-AT might be linked to the tumorigenesis, metastasis and poor prognosis of PRAD through Alzheimer's disease pathway according to varies of bioinformatics analysis." (PMID 37010714, 2023). "Similarly, HSPB1 was found to localize to plaques in transgenic mouse models of Alzheimer’s disease." (PMID 32323160, 2020). "And the results confirmed that there was a close connection among HSPB1, PIP5K1C and five key genes in pathway of Alzheimer’s disease (AD)." (PMID 37010714, 2023). "By multidimensional validation, we wondered that HSPB1 regulating the PIP5K1C-46721-AT might play an essential part in bone metastasis and distant metastasis of prostate adenocarcinoma through the Alzheimer’s disease pathway, which was also related to prognosis." (PMID 37010714, 2023). "Moreover, by multiple databases, we speculated that for PRAD patients with metastasis, HSPB1 could up-regulating the PIP5K1C − 46,721 − AT by the pathway of Alzheimer’s disease which was also related to prognosis." (PMID 37010714, 2023).
colon carcinoma (9 papers, 2014 to 2025). "HSPB1 (HSP27) overexpression is demonstrated to reverse the anti-tumor impact of miR-214 on colon cancer cell growth and resistance to 5-FU." (PMID 38166604, 2024). "The HSPB1 (Heat Shock Protein Beta-1) gene, which showed a significant change in right and left colon cancer, is known as a negative regulator of ferroptosis, one of the programmed cell deaths, and its high expression has been shown to influence drug resistance and cancer progression." (PMID 41441010, 2025). "Furthermore, Curcumin’s anti-cancer effects in colon cancer cells are modulated by HSPB1’s ability to induce reactive oxygen species (ROS) generation and autophagy." (PMID 36582202, 2022). "To confirm the effect of HSPB1 fragment on other tumor cell lines, we made lung tumors using CT26 colon carcinoma cells." (PMID 24465581, 2014). "HSPB1 was shown to increase the degradation of ubiquitinated proteins in response to stress stimuli triggered by TNF-α when interacting with the 26S portion of the proteasome in human leukemia (U937), murine embryogenic fibroblast, and rat colon carcinoma cells." (PMID 34571827, 2021). "However, in U937 human leukemic cells, MEF cells, macrophages and rat colon carcinoma REG cells, HSPB1 appears to enhance NF-κB activation in response to either etoposide or TNF-α treatment, suggesting that the outcome of NF-κB regulation by HSPB1 may vary with cell type or stimuli." (PMID 29662435, 2018).
hepatocellular carcinoma (9 papers, 2015 to 2024). A malignant tumor that arises from hepatocytes. "HRAS promotes hepatocellular carcinoma progression by upregulating HSPB1, reducing ferroptosis, and enhancing cell proliferation and invasion." (PMID 39315094, 2024). "Upregulation of HSPB1 is related to poor overall survival in hepatocellular carcinoma and promotes tumorigenesis." (PMID 37268925, 2023). "HBV regulates the growth of hepatoma cells via mir-304-5p/ATF7/ HSPB1 signal axis." (PMID 35150481, 2022). "A recent study of a hepatocellular carcinoma cell line showed that HSPB1 protects cells from cisplatin-induced death through an autophagy mechanism, and suggested a connection between autophagy-related gene 7 and HSPB1." (PMID 25962073, 2015). "By establishing a sora-resistant hepatocellular carcinoma cell line, we found that Heat Shock Protein Family B (small) Member 1 (HSPB1) was markedly upregulated in sora-resistant HCC cells." (PMID 37777559, 2023). "Further research has revealed that HSPB1 knockout led to a decrease in insulin levels and expression of growth factor-like binding protein 2, which may promote the proliferation and metastasis of hepatocellular carcinoma." (PMID 37268925, 2023). "A strong finding has also indicated that HSPB1 and HSPB6 formation results in a reduction in the progression of hepatocellular carcinoma." (PMID 37241227, 2023).
Parkinson disease (9 papers, 2011 to 2024). A progressive degenerative disorder of the central nervous system characterized by loss of dopamine producing neurons in the substantia nigra and the presence of Lewy bodies in the substantia nigra and locus coeruleus. "HspB1 and/or HspB5 accumulate in cortical Lewy bodies, Alzheimer disease plaques, neurofibrillary tangles, Rosenthal fibers of Alexander's-disease, Creutzfeldt-Jakob altered neurones as well as in synuclein deposit associated to Parkinson's disease or myopathy-associated inclusion body." (PMID 24278676, 2012). "Similarly, overexpression of HSPB1 has a potent protective anti-apoptotic effect against the damaging effects from α-synuclein in cell models of Parkinson’s disease." (PMID 36291591, 2022). "Given that HSPB1 increase has been reported in astrocytes across multiple neurological diseases with astrocyte reactivity, including AD and other tauopathies, Parkinson’s disease, or in brain ischemia, we can speculate that this is a conserved mechanism across diseases." (PMID 38507480, 2024). "Studies reported overexpression of HSPB1, CRYAB and HSP70 in the brains of AD and Parkinson's disease patients." (PMID 35099007, 2022).
colorectal cancer (8 papers, 2017 to 2025). A primary or metastatic malignant neoplasm that affects the colon or rectum. "Two genes involved in ferroptosis and lipid metabolism, FDFT1 and HSPB1, have been related to a poor prognosis in colorectal cancer, which is congruent with our own findings in COAD metastases." (PMID 36582202, 2022). "Moreover, it has been shown that HSPB1 accumulation reduces the apoptotic process induced by alkylating agents in colorectal cancer cells." (PMID 28903393, 2017). "Using Random Survival Forest (RSF) analysis with importance scoring, we identified seven key prognostic genes (CD24, SLC25A5, HSPB1, CD9, SPIMK1, LGALS4, and CEACAM5), which were subsequently designated as the Colorectal cancer Survival Signature (CSS)." (PMID 40777020, 2025).